PRPS1 (phosphoribosyl pyrophosphate synthetase 1)
Diseases named in the same sentence as PRPS1 in open-access papers (continued):
Sharing a sentence is not in itself a finding about the gene and the disease.
leukemia (3 papers, 2021 to 2025). A malignant (clonal) hematologic disorder, involving hematopoietic stem cells and characterized by the presence of primitive or atypical myeloid or lymphoid cells in the bone marrow and the blood. "To directly confirm the significance of the NUDT15 variant genotype and NT5C2 and PRPS1 mutations in thiopurine sensitivity of leukaemia cells in the intrinsic genes, we investigated 84 B‐cell precursor‐ALL (BCP‐ALL) cell lines." (PMID 34636169, 2021). "In the present study, we investigated the significance of variant NUDT15 genotype and NT5C2 and PRPS1 mutations in thiopurine activation and sensitivity of leukaemia cells using a large series of B‐cell precursor‐ALL (BCP‐ALL) and T‐cell ALL (T‐ALL) cell lines." (PMID 34636169, 2021).
lung carcinoma (3 papers, 2024 to 2025). "Consistently, PRPS1 2A mutant tumors were more sensitive to etoposide than PRPS1 WT tumors, just as in the PRPS1-deficient group, indicating that PRPS1 O-GlcNAcylation confers lung cancer cell resistance to chemoradiotherapy." (PMID 37308732, 2024). "We also measured OGT and PRPS1 O-GlcNAcylation levels in fresh frozen samples of lung cancer tissues obtained during surgery." (PMID 37308732, 2024). "Elevated PRPS1 O-GlcNAcylation promotes tumorigenesis and confers resistance to chemoradiotherapy in lung cancer." (PMID 37308732, 2024). "Notably, PRPS activity and PRPS1 O-GlcNAcylation were much higher in tumor tissues, implying that PRPS1 O-GlcNAcylation is involved in lung cancer tumorigenesis." (PMID 37308732, 2024). "Our findings suggest that PRPS1 O-GlcNAcylation could be used as a biomarker to predict etoposide or radiation resistance and as a treatment target in patients with lung cancer." (PMID 37308732, 2024). "Thus, reducing PRPS1 activity by silencing OGT could resensitize lung cancer cells to chemoradiotherapy." (PMID 37308732, 2024). "O-GlcNAcylation of PRPS1 triggers its hexamerization and inhibits AMPK-mediated PRPS1 phosphorylation, thus increasing its activity and promoting tumorigenesis in lung cancer." (PMID 39178944, 2024). "Two isoforms (PRPS1 and PRPS2) in lung cancer cells have a similar enzymatic function." (PMID 37308732, 2024).
lymphoma (3 papers, 2022 to 2025). A malignant (clonal) proliferation of B- lymphocytes or T- lymphocytes which involves the lymph nodes, bone marrow and/or extranodal sites. "•PRPS1 loss-of-function induces oxidative stress in Myc-driven lymphoma." (PMID 40446642, 2025). "Specifically, we discover that oxPPP-derived NADPH is necessary to drive the reactions catalyzed by TRXR and GSR, identifying inhibition of the PRPS1 isoform as a new potential therapeutic angle to sensitize cells to toxic levels of oxidative stress in these lymphomas." (PMID 39868212, 2025). "To test whether differences in allosteric feedback sensitivity to purines account for the phenotypes observed in PRPS2 KO lymphoma cells, we generated ALFA-tagged PRPS1 harboring superactive D52H and H193L mutations to exogenously overexpress in PRPS2 KO cells." (PMID 39868212, 2025). "This phenotype is specific to the Myc-regulated PRPS2 isoform, as knocking out the PRPS1 isoform does not impact viability in these lymphoma cells, suggesting that the Myc-dependent induction of oxidative metabolism may be linked to lymphoma cell viability via PRPS activity." (PMID 39868212, 2025). "Rather, we demonstrate how inherent differences in PRPS1 and PRPS2 activity can be leveraged to elicit opposing effects on redox homeostasis to selectively target Myc-overexpressing lymphomas with compounds acting on key oxidizing or reducing machineries." (PMID 39868212, 2025). "Each compound was tested at increasing concentrations in WT, PRPS1 KO and PRPS2 KO CA46 lymphoma cells such that normalized viability responses could be reported as an EC50 value." (PMID 39868212, 2025). "Employing a pharmacological screen, we demonstrate how targeting PRPS1 or PRPS2 elicits opposing sensitivity or resistance, respectively, to chemotherapeutic agents affecting the thioredoxin and glutathione network, thus providing a therapeutic blueprint for treating MYC-driven lymphomas." (PMID 39868212, 2025). "Mechanistically, we show that genetic inactivation of the PRPS2 isozyme, but not PRPS1, in MYC-driven lymphoma cells leads to elevated NADPH levels and reductive stress-mediated death." (PMID 39868212, 2025). "However, another study confirmed that in c-MYC-overexpressing malignant lymphoma cells, the gene expression of PRPS2 rather than PRPS1 is strongly regulated at the translational level to regulate purine synthesis." (PMID 36203561, 2022).
retinitis pigmentosa (3 papers, 2014 to 2024). Retinitis pigmentosa (RP) is an inherited retinal dystrophy leading to progressive loss of the photoreceptors and retinal pigment epithelium and resulting in blindness usually after several decades. "More recently, the first evidence of sector retinitis pigmentosa, which is known to have a more favourable prognosis compared to generalized retinitis pigmentosa, has been linked to the mutation p.S16F in PRPS1." (PMID 35741038, 2022).
congenital sensorineural hearing loss (2 papers, 2025). "As an additional negative control, we employed an ALFA-tagged hypomorphic PRPS1 A87T variant which has decreased ATP binding affinity and causes congenital sensorineural hearing loss (DFN2) in humans." (PMID 40446642, 2025).
depression (2 papers, 2021 to 2023). "The 6 top blood biomarkers with the strongest overall CFE for tracking and predicting both depression and mania, hence bipolar mood disorders, after the first four steps were NRG1, DOCK10, GLS, PRPS1, TMEM161B, and SLC6A4." (PMID 33828235, 2021). "A number of individual top biomarkers are known to be modulated by medications in current clinical use for treating depression, such as by lithium (NRG1, PRPS1, CD47), antidepressants (SLC6A4, DOCK10, NRG1, CD47) and the nutraceutical omega-3 fatty acids (GLO1, SLC6A4, CD47, GLS, HNRNPDL)." (PMID 33828235, 2021).
melanoma (2 papers, 2022 to 2025). A malignant, usually aggressive tumor composed of atypical, neoplastic melanocytes. "Taken together, these data suggested that NDUFS3-mediated melanoma progression was associated with changes in the activity of the nucleotide metabolic enzyme PRPS1." (PMID 40404919, 2025). "When AMPK was activated, the activity of PRPS1 was antagonized, thus leading to a marked decrease in purine nucleotide synthesis in melanoma cells." (PMID 40404919, 2025). "Subsequently, the results of analyzing the GEPIA database indicates that the mRNA level of PRPS1 is upregulated in melanoma samples." (PMID 40404919, 2025). "This study aimed to investigate the regulatory mechanism of PRPS1 in the malignant progression of melanoma." (PMID 36203561, 2022). "It is worth noting that the NRF2 activator/NRF2 inhibitor has a significant dose-response relationship in promoting/inhibiting the proliferation, invasion and migration of PRPS1 overexpression/PRPS1 knock-down melanoma cell." (PMID 36203561, 2022). "In contrast, the early apoptosis rate of PRPS1 knockdown melanoma cells was higher than that of the control group." (PMID 36203561, 2022). "In this study, our data demonstrated that PRPS1 is highly expressed in melanoma tissues and melanoma cell lines." (PMID 36203561, 2022). "EdU staining further showed that the growth of melanoma cells overexpressing PRPS1 was significantly faster than that of the control group, but the proliferation of cells with PRPS1 knockdown was slower than that of the control group." (PMID 36203561, 2022). "Conversely, A875 and SK-MEL-110 melanoma cells with stable knockdown of PRPS1 exhibited lower mRNA and protein levels of the apoptosis-related factors Bax and cleaved caspase-3 than the controls." (PMID 36203561, 2022). "Next, RT–PCR, western blotting, and flow cytometry assays were used to analyze the effects of PRPS1 on the cell cycle phase distributions of melanoma cells." (PMID 36203561, 2022). "We also demonstrated that overexpression of PRPS1 promoted melanoma tumor proliferation, migration, and invasion in vitro and in vivo and inhibited melanoma cell apoptosis." (PMID 36203561, 2022). "Based on qPCR and western blotting analysis, we found that the mRNA and protein levels of the apoptosis-related factor Bcl2 were significantly increased in A875 and SK-MEL-110 melanoma cells overexpressing PRPS1." (PMID 36203561, 2022). "The mRNA and protein expression levels of PRPS1 in melanoma cell lines were higher than those in HEM cell lines." (PMID 36203561, 2022). "Our study found that NRF2 can regulate the transcription of PRPS1 and then regulate the proliferation and metastasis of melanoma." (PMID 36203561, 2022). "In contrast, knockdown of PRPS1 suppressed proliferation, migration, and invasion while advancing apoptosis in melanoma." (PMID 36203561, 2022). "It is worth noting that the expression of PRPS1 in metastatic melanoma patients was higher than that in primary melanoma patients." (PMID 36203561, 2022). "The NRF2 activator significantly increased the proliferation rate of PRPS1-overexpressing melanoma cells, while the NRF2 inhibitor significantly decreased the proliferation rate of PRPS1-knockdown melanoma cells." (PMID 36203561, 2022). "This is the first study to provide data by systematically analyzing the function and regulatory mechanism of PRPS1 in melanoma." (PMID 36203561, 2022). "The RT–PCR results showed that compared to the control, the mRNA levels of cell cycle proteins, such as cyclin E1 and CDK2, were enhanced in PRPS1-overexpressing melanoma cells, but the mRNA level of P16 was inhibited." (PMID 36203561, 2022). "The abnormally high expression of PRPS1 promotes the growth and metastasis of melanoma in vivo and in vitro." (PMID 36203561, 2022). "To investigate the role of PRPS1 in the proliferation and malignant progression of melanoma, we analyzed PRPS1 expression in melanoma based on the GEPIA database." (PMID 36203561, 2022).
melanoma (continued). "Our study demonstrated that PRPS1 is highly expressed in melanoma and promotes melanoma proliferation and metastasis and decreases melanoma cell apoptosis." (PMID 36203561, 2022). "In the plate colony formation assay, we found that the colony forming ability of melanoma cells overexpressing PRPS1 was significantly stronger than that of the control group, and the melanoma cells with PRPS1 knockdown showed the opposite results." (PMID 36203561, 2022). "To explore the function of PRPS1 in melanoma cells, we successfully established stable PRPS1 overexpression and knockdown in A875 and SK-MEL-110 melanoma cell lines." (PMID 36203561, 2022). "In the Transwell invasion experiment, we also found that overexpression of PRPS1 promoted the invasion of melanoma cells, while knockdown of PRPS1 suppressed the invasion of melanoma cells." (PMID 36203561, 2022). "We thoroughly investigated the effect of PRPS1 on the invasion and malignant progression of melanoma." (PMID 36203561, 2022). "Taken together, the results suggest that PRPS1 drastically promotes the potential for tumor proliferation, malignancy, and metastasis of melanoma in vitro and in vivo." (PMID 36203561, 2022). "Furthermore, the expression levels of PRPS1 were significantly elevated in 87.6% of 89 melanoma samples and 50% of 10 nevi samples." (PMID 40404919, 2025). "However, the number of TUNEL-positive cells in PRPS1-knockdown melanoma cells was greater than that in the controls." (PMID 36203561, 2022). "In addition, by flow cytometry analysis, we found that the percentage of early apoptosis in melanoma cells with PRPS1 overexpression was lower than that in the control group." (PMID 36203561, 2022). "The CCK8 results showed that stable overexpression of PRPS1 markedly promoted melanoma cell growth." (PMID 36203561, 2022). "Notably, western blotting demonstrated that the higher the expression of PRPS1 was, the stronger the ability of melanoma cells to metastasize." (PMID 36203561, 2022). "We first showed that PRPS1 could promote the growth, migration, and invasion of melanoma and prevent melanoma cell apoptosis." (PMID 36203561, 2022). "Moreover, western blotting was performed to assess the expression levels of EMT-associated proteins in the stable PRPS1 overexpression and knockdown A875 and SK-MEL-110 melanoma cell lines." (PMID 36203561, 2022). "Furthermore, we found NRF2 is an upstream transcription factor of PRPS1 that drive malignant progression of melanoma." (PMID 36203561, 2022). "Furthermore, TUNEL staining showed that the number of TUNEL-positive cells in PRPS1-overexpressing melanoma cells was less than that in the control group." (PMID 36203561, 2022). "In conclusion, these results demonstrate that PRPS1 promotes the proliferation, malignancy, and metastasis of melanoma, which may be related to NRF2." (PMID 36203561, 2022). "The western blotting results showed that the protein levels of cyclins such as cyclin E1 and CDK2 were increased in PRPS1-overexpressing melanoma cells, while the level of P16 was decreased compared with the control group, while the opposite was true in PRPS1 knockdown A875 and SK-MEL-110 cells." (PMID 36203561, 2022). "In this study, we first confirmed that PRPS1 is highly expressed in melanoma." (PMID 36203561, 2022). "Furthermore, an immunohistochemical (IHC) method was used to detect the expression of PRPS1 in melanoma tissues (melanoma in situ and metastatic melanoma) and normal nevi." (PMID 36203561, 2022). "Our findings provide a theoretical basis for PRPS1 as a potential therapeutic target for melanoma." (PMID 36203561, 2022). "In addition, we analyzed the correlation of PRPS1 with melanoma in situ and melanoma metastasis based on the UALCAN database." (PMID 36203561, 2022). "Next, we performed animal experiments to confirm whether the abnormal expression of PRPS1 affects the progression of melanoma proliferation in vivo." (PMID 36203561, 2022).
melanoma (continued). "Here, we found PRPS1 was upregulated in melanoma and melanoma cells." (PMID 36203561, 2022). "Importantly, PRPS1 was highly expressed in 90.7% (68/75) of primary melanomas, 71.4% (10/14) of metastatic melanomas, and 50% (5/10) of nevus tissue samples." (PMID 36203561, 2022). "We further analyzed the mechanism by which PRPS1 regulates the malignant progression of melanoma." (PMID 36203561, 2022). "We found that the expression of PRPS1 was dramatically upregulated in melanoma." (PMID 36203561, 2022). "We further explored the mechanisms by which NRF2 regulates PRPS1 in melanoma cells." (PMID 36203561, 2022). "Therefore, we speculated that NDUFS3 may affect the proliferation of melanoma cells through AMPK phosphorylated PRPS1 mediated nucleotide metabolism." (PMID 40404919, 2025). "However, it is still elusive whether PRPS1 is related to the proliferation and metastatic progression of melanoma." (PMID 36203561, 2022). "In addition, our data indicated that PRPS1 could promote the proliferation and migration and invasion of melanoma both in vitro and in vivo." (PMID 36203561, 2022). "However, the mechanism by which PRPS1 regulates the malignant progression of melanoma remains unclear." (PMID 36203561, 2022). "Next, we evaluated whether NRF2 could influence the effects of PRPS1 on melanoma cell metastasis." (PMID 36203561, 2022). "However, it was unclear whether NRF2 could affect the proliferation and metastasis of melanoma cells by regulating the expression level of PRPS1." (PMID 36203561, 2022). "The results demonstrated that PRPS1 could promote the proliferation of melanoma cells in vitro." (PMID 36203561, 2022). "Therefore, we investigated whether NRF2 affects the malignant progression of melanoma by regulating PRPS1." (PMID 36203561, 2022). "Following treatment with the AMPK inhibitor, NDUFS3-knockdown melanoma cells exhibited increased cell proliferation, possibly due to the downregulation of p-AMPK(T172) expression and the increase in PRPS1 activity." (PMID 40404919, 2025). "Collectively, these results suggested that NDUFS3 downregulates/upregulates melanoma cell proliferation by promoting/inhibiting AMPK phosphorylation and reducing/promoting PRPS1 activity." (PMID 40404919, 2025). "The levels of PRPS1 and NRF2 in the tumors were positively correlated with the melanoma tumor volumes and the degree of melanoma metastasis in each group." (PMID 36203561, 2022). "The level of PRPS1 in the stably transfected A875 and SK-MEL-110 melanoma cells was measured by qPCR and western blot analysis." (PMID 36203561, 2022). "In 110 melanoma cells, the abundance of NRF2 combined with PRPS1 primer 1 (1403-1414) was increased by 2.8 times and that combined with PRPS1 primer 2 (1477-1487) was increased by 7.1 times (right)." (PMID 36203561, 2022). "However, the effect of PRPS1 on melanoma proliferation and metastasis remains unclear." (PMID 36203561, 2022). "In contrast, knockdown of PRPS1 reduced A875 and SK-MEL-110 melanoma cell proliferation." (PMID 36203561, 2022). "Next, we detected the expression of PRPS1 in HEM, A875 and SK-MEL-110 melanoma cell lines." (PMID 36203561, 2022). "Melanoma cells overexpressing NDUFS3 were incubated with an AMPK activator, leading to cell growth inhibition, which may be due to increased p-AMPK(T172) expression and decreased PRPS1 activity." (PMID 40404919, 2025). "The ChIP–qPCR results showed that NRF2 was recruited to PRPS1 primer 1 (-1403-1414), which was 3.1 times that of the negative control, and PRPS1 primer 2 (1477-1487), which was 9.7 times that of the negative control in A875 melanoma cells (left)." (PMID 36203561, 2022).
non-syndromic hearing loss (2 papers, 2021 to 2022). "To date, five X-linked genes have been found to be related to the etiology of non-syndromic hearing loss (NSHL): PRPS1 (DFNX1, OMIM:311850), POU3F4 (DFNX2, OMIM:300039), SMPX (DFNX4, OMIM:300226), AIFM1 (DFNX5, OMIM:300169) and COL4A6 (DFNX6, OMIM:303631)." (PMID 33860785, 2021).
albinism (1 paper, 2021). A congenital disorder characterized by partial or complete absence of melanin pigment in the eyes, hair, or skin. "Here, we identified a new chloroplast ribosomal protein ASL4/PRPS1 in rice, mutation of which caused albinism." (PMID 34046768, 2021).
asthma (1 paper, 2016). "In addition, it is pertinent to note with the exception of one gene “PRPS1” (brown module), these asthma-associated genes were again restricted to the blue module." (PMID 26922672, 2016).
atrophy of (1 paper, 2014). "Here we show that mild signs of cerebellar and parietal atrophy can be seen in both subject II-2 and subject II-1, thus providing first evidence for structural central nervous system damage in PRPS1- disease." (PMID 24528855, 2014). "As atrophy is very mild, it might have been present also in previous PRPS1 subjects, yet not been recognized." (PMID 24528855, 2014).
Brain atrophy (1 paper, 2014). Partial or complete wasting (loss) of brain tissue that was once present. "Finally, our findings show that brain atrophy might be more common in PRPS1-disorders than previously thought." (PMID 24528855, 2014).
diabetes (1 paper, 2015). "This transcription factor leads to the inhibition of FHL1, IARS2, ARL6IP5, PSIP1 and PRPS1, some of which have been implicated in processes that are involved in the progression of different conditions leading to diabetes." (PMID 26302420, 2015).
Floating-Harbor syndrome (1 paper, 2022). Floating-Harbor syndrome is a genetic developmental disorder characterized by facial dysmorphism, short stature with delayed bone age, and expressive language delay. "Examples of reclassification of VUS in our study include a novel and distinctive phenotype for the SRCAP gene, previously associated with Floating-Harbor syndrome only, a VUS in PRPS1 recently also reported by others, and small genotype-phenotype case series for LMBRD2 and PAX3." (PMID 35710456, 2022).